AHR (aryl hydrocarbon receptor)
Diseases named in the same sentence as AHR in open-access papers (continued):
Sharing a sentence is not in itself a finding about the gene and the disease.
ovarian endometriosis (1 paper, 2021). A non-neoplastic disorder characterized by the growth of endometrial tissue in the ovaries. "We analyzed VDR and AHR expression in the stroma of the tissues, both for the three phases of the endometrium and for ovarian endometriosis." (PMID 34155552, 2021). "We found significantly higher expression of VDR and AHR in the nuclei of glandular cells derived from ovarian endometriosis compared to the three phases of the normal endometrium." (PMID 34155552, 2021). "We identified a significant enhanced AHR expression with a median IRS value of 1 in nuclei of glandular ovarian endometriosis (p < 0.03) compared to three phases of normal endometrial tissue." (PMID 34155552, 2021). "Furthermore, our data suggest that expression of VDR and AHR is mutually exclusive in ovarian endometriosis." (PMID 34155552, 2021). "Spearman’s analysis revealed a negative correlation in the expression of VDR and AHR in the nuclei of the glandular cells from ovarian endometriosis, which led us to speculate that VDR and AHR expression is mutually exclusive in this condition." (PMID 34155552, 2021). "No AHR expression was found in the cytoplasm of ovarian endometriosis samples." (PMID 34155552, 2021).
overnutrition (1 paper, 2025). An imbalanced nutritional status resulting from excessive intake of nutrients. "Under conditions of overnutrition, AHR deletion significantly decreased hepatic levels of the primary free bile acid Chenodeoxycholic Acid (CDCA) and the primary conjugated bile acids Taurochenodeoxycholic Acid (TCDCA) and Glycochenodeoxycholic Acid (GCDCA)." (PMID 41516226, 2025).
pancreatic diseases (1 paper, 2024). "Despite this association, the mechanistic role of AHR as a linchpin molecule in EDC exposure-related pathogenesis of pancreatic diseases and cancer remains unexplored." (PMID 38612627, 2024). "Nevertheless, further mechanistic studies investigating the role of BPA-regulated AHR pathways in the pathogenesis of pancreatic diseases and cancer are warranted." (PMID 38612627, 2024). "The next section will describe the effects of the dioxin and dioxin-like compound-regulated AHR signaling axis on the pathogenesis of pancreatic diseases and cancer." (PMID 38612627, 2024). "Nevertheless, the underlying mechanisms by which PAH exposure mediates the development of pancreatic diseases and cancer through the aryl hydrocarbon receptor (AHR) signaling pathway remain unexplored." (PMID 38612627, 2024). "This review comprehensively examines the involvement of AHR in EDC exposure-mediated regulation of pancreatic pathogenesis, emphasizing AHR as a potential therapeutic target for the pathogenesis of pancreatic diseases and cancer." (PMID 38612627, 2024). "However, the effects of BPA on AHR signaling involving development of pancreatic diseases and cancer remain to be further investigated." (PMID 38612627, 2024). "However, the underlying mechanisms connecting heavy metal exposure-mediated AHR signaling regulation to the development of pancreatic diseases and cancer remain unknown." (PMID 38612627, 2024). "The role of AHR as a molecular interface between EDC exposure and the development of various pancreatic diseases, including cancer, is summarized below." (PMID 38612627, 2024). "The role of the non-canonical AHR pathway in various human diseases, including pancreatic diseases and cancer, remains largely unexplored." (PMID 38612627, 2024). "However, there is a gap in our understanding regarding AHR’s molecular and mechanistic roles in the EDC-mediated development of various pancreatic diseases and cancer." (PMID 38612627, 2024).
porphyria (1 paper, 2010). Porphyria is a group of diseases in which substances called porphyrins build up, negatively affecting the skin or nervous system. "This idea is supported by the findings of AHR-dependent heme synthesis dysregulation in adult mice, and of porphyria in dioxin-exposed mammals and birds, including humans." (PMID 20463971, 2010).
proliferative diabetic retinopathy (1 paper, 2021). Advanced retinopathy due to diabetes mellitus characterized by the formation of new vessels in the retina. "Collectively, these findings provide evidence that the AhR agonist VAF347 could be a potentially novel therapeutic for non-proliferative diabetic retinopathy." (PMID 33919327, 2021). "Nevertheless, our current study provides strong evidence that the AhR agonist-VA347 could be a good therapeutic candidate for early-stage non-proliferative diabetic retinopathy." (PMID 33919327, 2021).
renal clear cell carcinoma (1 paper, 2021). "Another study has demonstrated that AhR expression is not related to pathological T stage in renal clear cell carcinoma." (PMID 34290693, 2021).
renal osteodystrophy (1 paper, 2020). Abnormalities of bone mineral metabolism associated with chronic kidney disease. "The IS/AhR/NFATc1 pathway prevents the CKD-associated deterioration of bone metabolism, and therefore, AhR antagonists may serve as novel drugs for renal osteodystrophy." (PMID 32429048, 2020).
renal tumor (1 paper, 2020). "We concluded that AhR translocation could be included as a marker of sensitivity to AF in sensitive renal tumor cells of different histological origin, in Phase II clinical trials." (PMID 32443455, 2020).
Respiratory tract infection (1 paper, 2019). An infection of the upper or lower respiratory tract. "For instance, several epidemiological studies have linked early life exposure to pollutants that act through the aryl hydrocarbon receptor (AHR) with increased wheezing, decreased antibody responses to vaccination, and increased incidence of ear and respiratory tract infections later in life." (PMID 31391494, 2019).
Right ventricular hypertrophy (1 paper, 2022). In this case the right ventricle is more muscular than normal, causing a characteristic boot-shaped (coeur-en-sabot) appearance as seen on anterior- posterior chest x-rays. "All three PAH mice showed comparable RVSP and right ventricular hypertrophy, indicating that the AhR pathway is not necessary to induce PAH but may contribute to PAH progression." (PMID 34528097, 2022).
salmonellosis (1 paper, 2023). Infections with bacteria of the genus salmonella. "This study discloses the promising alternative therapy of combining postbiotic and VD3 for invasive Salmonellosis and the pivotal role of AhR pathway." (PMID 36678175, 2023).
sarcoidosis (1 paper, 2020). Sarcoidosis is a multisystemic disorder of unknown cause characterized by the formation of immune granulomas in involved organs. "The proteins differentially expressed between controls vs sarcoidosis and progressive vs. non-progressive sarcoidosis cases also mapped to Aryl hydrocarbon receptor signaling." (PMID 32764642, 2020).
sarcopenia (1 paper, 2025). Progressive decline in muscle mass due to aging which results in decreased functional capacity of muscles. "Interestingly, KYN's effects on oxidative stress and lipid peroxidation occur independently of direct activation of AhR, making KYN metabolic inhibition a potential preventive approach for sarcopenia." (PMID 39963429, 2025).
scleroderma (1 paper, 2020). Scleroderma is a rare autoimmune connective tissue disorder characterized by abnormal hardening of the skin and, sometimes, other organs. "Indeed, others have shown that AHR plays a role in controlling MMP1 production in scleroderma and periodontal ligament cells." (PMID 32439897, 2020).
serous ovarian cancers (1 paper, 2021). "We evaluated the clinical outcome of 265 patients with high-grade serous ovarian cancers available in The Cancer Genome Atlas (TCGA) stratified by TIL expression and 44 genes related to tryptophan catabolism and AHR signaling." (PMID 34025677, 2021).
serous ovarian tumors (1 paper, 2021). "During serous ovarian tumor formation, activated AHR in the cytoplasm could cooperate with SRC, enter cell nuclei, bind to AHR nuclear translocator (ARNT) together with TATA-Box Binding Protein (TBP), and act on DNA to initiate AHR-responsive genes to cause tumor or cancer initiation." (PMID 34440070, 2021). "Our results showed that there is indeed a tight correlation between AHR and EMT as the degree of malignancy develops in serous ovarian tumors, just like other malignancy." (PMID 34440070, 2021).
Serratia Infections (1 paper, 2022). Infections with bacteria of the genus SERRATIA. "The PC3 and PC4 captured 7.3% and 4.1% of the variance, the replicates of AhR-antagonist/infection, dsAhR/infection and dsKLF10/infection were clustered more closely, which separated from the clusters of Serratia infection and dsGFP/infection." (PMID 35397616, 2022).
Skeletal myopathy (1 paper, 2024). "The present study examined the role of chronic AHR activation in the skeletal myopathy associated with chronic cigarette smoke exposure." (PMID 38333944, 2024).
skin sensitisation (1 paper, 2023). "As dendritic cells interact with both keratinocytes and T cells which are mechanistically involved in the pathogenesis of skin sensitisation, the expression of immune-inhibitory molecules PD-L1 and AhR was experimentally blocked and altered on dendritic cell-similar THP-1." (PMID 37147507, 2023).
somatotrophinomas (1 paper, 2020). "Whereas AIP germline mutations are most classically associated with somatotrophinomas, AHR may be more relevant to corticotrophinomas as in our patient." (PMID 31996203, 2020). "AHR may also have AIP-independent roles in pituitary tumorigenesis as AHR but not AIP expression is reduced in GNAS-mutated somatotrophinomas, and AHR activation increases the transcription of CDKN1B, which is another tumour suppressor gene implicated in pituitary and other endocrine tumours." (PMID 31996203, 2020). "Loss of AHR stabilisation is postulated to be contributory to AIP-associated pituitary tumorigenesis, with somatotrophinomas from patients with germline AIP mutations typically showing decreased cytoplasmic and absent nuclear AHR staining." (PMID 31996203, 2020).
somatotropinoma (1 paper, 2020). "In this context, it is worth mentioning that the aryl hydrocarbon receptor (AHR)-interacting protein (AIP) has been proven critical in somatotropinoma physiopathology and clinical expression." (PMID 33281746, 2020). "This is the first demonstration of a recurrent somatic deletion in the exon 10 of the AHR gene in somatotropinomas." (PMID 33281746, 2020). "Sequence analysis of DNA and RNA from somatotropinoma histological samples derived from patients carrying or not the germline rs2066853 AHR variant revealed an in frame deletion on AHR coding sequence c.1246-1254 as compared to patients’ matched germline DNA and pituitary normal tissue." (PMID 33281746, 2020). "A degenerated letter codes in the region corresponding to AHR exon 10 (c.1239-c.2056) was detected in somatotropinomas-derived DNA but not in that of matched germline and pituitary normal tissue." (PMID 33281746, 2020).
stable angina (1 paper, 2024). "Thus, patients with the TCF21 gene CC genotype may, through the increased effect of AHR, on inflammatory gene expression activation, contribute to the increased risk of stable angina and STEMI." (PMID 38250610, 2024).
staphylococcus aureus infection (1 paper, 2025). An infectious process in which the bacteria Staphylococcus aureus is present. "WikiPathways analysis emphasized high enrichment scores in IL-18 signaling pathway, aryl hydrocarbon receptor pathway, T-cell antigen receptor pathway during staphylococcus aureus infection, and Th17 cell differentiation pathway." (PMID 41333466, 2025).
stricture (1 paper, 2023). "Another study from Southeast China found an association between CD and AHR gene polymorphism in a group of patients that the genotypes of AHR (rs2158041) may be a CD susceptibility gene (especially for ileal CD and stricture CD)." (PMID 37942478, 2023).
teratoma (1 paper, 2022). A non-seminomatous germ cell tumor characterized by the presence of various tissues which correspond to the different germinal layers (endoderm, mesoderm, and ectoderm). "On the other hand, AhR has emerged as a regulatory factor in pluripotency and stemness in different cell types, including undifferentiated human teratoma cells." (PMID 35619220, 2022).
thrombophilia (1 paper, 2024). A condition characterized by an abnormally high level of thrombi. "In addition, the SARS-CoV-2 virus stimulates the aryl hydrocarbon receptor (AhR) and increases KN levels, which leads to the systemic AhR activation syndrome (SAAR) that intensifies inflammation, induces thrombophilia, and contributes to organ damage." (PMID 38649417, 2024).
toxoplasmosis (1 paper, 2015). A parasitic disease contracted by the ingestion or fetal transmission of toxoplasma gondii. "It is unclear whether the infection-induced perturbations to the gut microbiota that occur during toxoplasmosis influence AHR activity, but T. gondii can also produce the AHR agonist lipoxin A4, and the AHR has been implicated in the direct sensing of pathogen-associated molecular patterns." (PMID 26010337, 2015). "For example, L-kynurenine, which is generated by tryptophan degradation catalyzed by the IFN-γ induced enzyme indoleamine 2,3 dioxygenase, is found in multiple tissues during toxoplasmosis and acts as an AHR agonist." (PMID 26010337, 2015). "Although the AHR can contribute to Treg development and T cell IL-10 production, processes that constrain the immune response during toxoplasmosis, no deficiencies in these pathways were observed in infected Ahr-/- animals." (PMID 26010337, 2015). "Notably, FoxP3- T-bet+ Th1 cells are thought to be the critical source of IL-10 during toxoplasmosis, but since previous studies have shown that the AHR is not expressed at detectable levels in Th1 cells it was unlikely that AHR activity would directly affect IL-10 production by this population." (PMID 26010337, 2015).
viral myocarditis (1 paper, 2018). Myocarditis that is caused by an infection with a viral agent. "It is possible that AhR modulates the inflammatory response in viral myocarditis." (PMID 29984241, 2018). "No study has examined the relationship between AhR and viral myocarditis." (PMID 29984241, 2018).
vitamin A deficiency (1 paper, 2017). Deficiency of vitamin A due to malnutrition, malabsorption, or dietary lack. "Furthermore, 2,3,7,8-Tetrachlorodibenzo-p-dioxin, by activating AhR, is teratogenic by causing vitamin A deficiency." (PMID 28264465, 2017).
tumor (877 papers, 2005 to 2026). "Elevated expression of AHR and its targets in the tumor microenvironment has been associated with cancer-driven immune evasion." (PMID 41357201, 2025). "To assess tumor infiltration by AhR-deficient NK cells, we inoculated MCA101-OVA tumors to Nrc1*AhRΔ mice and WT littermates, fed on I3C diet." (PMID 41331250, 2025). "In tumor‐associated macrophages (TAMs), AhR regulates the shift between pro‐inflammatory M1 and anti‐inflammatory M2 macrophages." (PMID 40103267, 2025). "While indole compounds show therapeutic potential in anti-inflammatory and immune tolerance via AHR activation, their long-term use requires caution due to possible side effects, including increased infection susceptibility and tumor immune escape." (PMID 41155173, 2025). "For example, tryptophan metabolites have been shown to exert dual roles, namely that they enhance ICB efficacy through modulating tumor-associated macrophages but also promote tumor progression via IL4I1-mediated AhR activation." (PMID 41169397, 2025). "Beyond T cells, 2-HG also alters the phenotype of tumor-associated macrophages (TAMs), producing an immunosuppressive environment by altering tryptophan metabolism and aryl hydrocarbon receptor (AhR) activation." (PMID 40647477, 2025). "Certain metabolites, particularly those linked to indole-3-pyruvate (I3P), drive M2-like polarization of tumor-associated macrophages (TAMs) through AhR signaling, fostering immune suppression and tumor growth." (PMID 40666095, 2025). "Hezaveh's experiments found that in pancreatic ductal adenocarcinoma (PDAC), removing dietary tryptophan reduces AhR activity in tumor‐associated macrophages (TAMs) and promotes the accumulation of TNF‐α+IFN‐γ+CD8+ T cells in the tumor." (PMID 40103267, 2025). "Mechanistic studies indicate that AhR exerts its tumor-suppressive functions by maintaining genomic stability, regulating cell cycle progression, and suppressing tumor-associated inflammatory responses." (PMID 41585883, 2025). "The AhR plays a pivotal role in driving metabolic reprogramming in tumor cells by modulating genes associated with proliferation, migration, invasion, immunosuppression, and resistance to chemotherapy and immunotherapy." (PMID 40149846, 2025). "Recent work demonstrates that microbial indoles can also activate AhR in tumor-associated macrophages (TAMs), driving immune suppression and accelerating pancreatic cancer growth." (PMID 41339918, 2025). "In the DEG analysis in the SCAN-B cohort, AHR-high expression was associated with hypoxia in ER+ tumours only." (PMID 40646277, 2025). "We confirmed that granzyme B production upon anti-PD1 treatment was impaired in tumor-infiltrating AhR-deficient CD8 T cells, contrasting with granzyme B production by WT CD8 T cells being similar in both diet groups." (PMID 41331250, 2025). "AhR upregulation causes an increase in PD-1 expression in the tumor environment, potentially promoting immune evasion and tumor progression." (PMID 41155994, 2025). "It inhibited the expression of AhR and M2-type tumor associated macrophages polarization, thereby promoting tumor immunity and inhibiting the growth of colitis-associated colorectal cancer (CAC) caused by colonic inflammation." (PMID 40066456, 2025). "F. nucleatum derived OMVs can also impair T cell function and blunt immunotherapy response through TDO2/AHR activation of tumour‐associated macrophages." (PMID 41216129, 2025). "Indole derivatives (e.g., ILA) can reprogram macrophage polarization via AhR-linked signaling, dampen pro-tumor cytokines, and reduce proliferation while promoting apoptosis." (PMID 41339918, 2025). "Research on IDO2 in GBM is limited, but it has been implicated in immune evasion through the Kyn–AhR pathway in multiple tumour types." (PMID 40471422, 2025). "AHR regulates multiple stages of tumorigenesis, including cell proliferation, angiogenesis, tissue invasion, tumor-associated inflammation, and metastasis." (PMID 39450255, 2024).